MIR298 (microRNA 298)
Synonyms: hsa-mir-298; MIRN298
Gene: MicroRNA gene on chromosome 20 (58,818,226 to 58,818,313, reverse strand). Ensembl gene ENSG00000216031.
Gene Ontology:
Biological process: miRNA-mediated post-transcriptional gene silencing
Homologues: Orthologues: chimpanzee ptr-mir-298 (100% identical), macaque mml-mir-298 (95% identical).